CRAT (carnitine O-acetyltransferase)
Description:
Catalyzes the reversible transfer of acyl groups from carnitine to coenzyme A (CoA) and regulates the acyl-CoA/CoA ratio. Also plays a crucial role in the transport of fatty acids for beta-oxidation. Responsible for the synthesis of short- and branched-chain acylcarnitines. Active towards some branched-chain amino acid oxidation pathway (BCAAO) intermediates. Trans-2-enoyl-CoAs and 2-methylacyl-CoAs are poor substrates.
Synonyms: CAT; CAT1; NBIA8
Tractability: Small molecule: a structure with a bound ligand is known. Antibody: UniProt places it where antibodies can reach, with high confidence. PROTAC: ubiquitination databases record sites on it; its protein half-life has been measured.
Target class: Group translocator; Transporter
Gene: Protein-coding gene on chromosome 9 (129,094,142 to 129,111,313, reverse strand). Ensembl gene ENSG00000095321.
Subcellular location: Endoplasmic reticulum; Peroxisome; Mitochondrion inner membrane; Mitochondrion (Isoform 1); Peroxisome (Isoform 2)
Subcellular location (Human Protein Atlas): Cytosol; Golgi apparatus
Pathways (Reactome):
Metabolism: Beta-oxidation of pristanoyl-CoA; Branched-chain amino acid catabolism
Protein localization: Peroxisomal protein import
Gene Ontology:
Molecular function: acyl-CoA oxidase activity; carnitine O-acetyltransferase activity; carnitine O-octanoyltransferase activity; carnitine O-acyltransferase activity; acyltransferase activity
Biological process: carnitine metabolic process, CoA-linked; fatty acid beta-oxidation using acyl-CoA oxidase; medium-chain fatty acid metabolic process; short-chain fatty acid metabolic process; branched-chain amino acid catabolic process; fatty acid metabolic process
Cellular component: mitochondrion; peroxisome; cytosol; mitochondrial inner membrane; peroxisomal matrix; endoplasmic reticulum
Genetic constraint (gnomAD): Loss-of-function variants: 66 observed, 72.94 expected, observed/expected ratio (o/e) 0.9, 90% interval 0.74 to 1.11. The upper end of that interval is the gene's LOEUF score, 1.11, which puts it in group 4 of 6, group 1 being the genes least tolerant of losing a copy. Missense variants: 744 observed, 847.67 expected, observed/expected ratio (o/e) 0.88, 90% interval 0.83 to 0.93. Synonymous variants: 321 observed, 341.28 expected, observed/expected ratio (o/e) 0.94, 90% interval 0.86 to 1.03.
Homologues: Orthologues: chimpanzee CRAT (99% identical), chimpanzee CRAT (98% identical), macaque CRAT (97% identical), dog CRAT (92% identical), mouse Crat (91% identical), rat Crat (91% identical), guinea pig CRAT (89% identical), pig CRAT (83% identical), tropical clawed frog crata (76% identical), zebrafish crata (73% identical), zebrafish CRAT (68% identical), Drosophila melanogaster CG5122 (38% identical), and 3 more. Paralogues in human: CHAT (41% identical), CROT (32% identical), CPT1A (32% identical), CPT1B (32% identical), CPT1C (30% identical), CPT2 (30% identical).
Diseases named in the same sentence as CRAT in open-access papers:
CRAT is named in the same sentence as 31 diseases in open-access papers, as found by Europe PMC text mining. Sharing a sentence is not in itself a finding about the gene and the disease. The quoted sentences say what the papers report.
Obesity (4 papers, 2017 to 2023). Accumulation of substantial excess body fat. "Additionally, these ketogenic athletes presented nearly eight times larger acylcarnitine content as carbohydrate-diet controls pre-exercise, which intricately has been associated with obesity and CrAT dysfunction in animal models." (PMID 33921022, 2021). "AgRP-specific CrAT knockout animals were shown to have severe metabolic inflexibility, characteristic of type II diabetics and obesity." (PMID 33921022, 2021). "In fact, CrAT activity, known to regulate substrate switching and glucose tolerance, has been found diminished in obesity and diabetes." (PMID 28134772, 2017).
breast carcinoma (3 papers, 2020 to 2023). "L-carnitine, short-chain acylcarnitines, and three carnitine-mediated enzymes: carnitine palmitoyltransferase 1 A (CPT1A), carnitine palmitoyltransferase 2 (CPT2), and carnitine acetyltransferase (CRAT) were all up-regulated in breast cancer tissues." (PMID 37120513, 2023). "In the present study, we examined the protein expression of the three remaining components of the carnitine system (CACT, CPT2, and CrAT) and confirmed their expression and deregulation in canine mammary tumor tissues and cells." (PMID 34679988, 2021). "Remarkably, the expressions of CPT 2 and CRAT were found for the first time to be altered in breast cancer." (PMID 32641979, 2020). "CPT 1A, CPT 2, and CRAT, which are extensively involved in carnitine system-mediated fatty acid β-oxidation pathway were also found to be abnormally expressed in breast cancer." (PMID 32641979, 2020).
melanoma (3 papers, 2025). A malignant, usually aggressive tumor composed of atypical, neoplastic melanocytes. "In contrast to our observations in OC, it was demonstrated that knockdown of CRAT suppressed melanoma metastasis, indicating a cancer-type-specific role for CRAT in cancer metastasis." (PMID 39828731, 2025). "Knockdown of FAO-related genes, such as CROT or CRAT, in a melanoma cell line led to a significant delay in metastasis in the xenograft model." (PMID 41155168, 2025). "The effects of modulating CRAT expression in other studies are mixed, with some demonstrating CRAT overexpression inhibits ovarian cancer growth and OXPHOS, whereas others found that CRAT depletion inhibits OXPHOS and melanoma metastasis." (PMID 41216931, 2025).
diabetes (2 papers, 2017 to 2022). "While our goal herein was to use CrAT deletion as a tool to mimic and achieve overload, it is also noteworthy that CrAT activity itself declines with age and diabetes." (PMID 35230975, 2022).
Glucose intolerance (2 papers, 2014 to 2017). Glucose intolerance (GI) can be defined as dysglycemia that comprises both prediabetes and diabetes. "In the skeletal muscle, knockdown of the enzyme carnitine acetyltransferase (CrAT), which preferentially converts short- and medium-chain fatty acids to acylcarnitines, leads to increased amounts long chain acylcarnitines in association with glucose intolerance." (PMID 28420087, 2017). "Recently the pivotal role of CrAT in acetyl-CoA metabolism was confirmed since experiments with CrATM−/− knock-out mice showed that absence of CrAT leads to accumulation of medium and long chain acylcarnitines in muscles and subsequently to glucose intolerance via overloaded mitochondria." (PMID 24962334, 2014).
ovarian carcinoma (2 papers, 2025). A malignant neoplasm originating from the surface ovarian epithelium. "Our bioinformatics analysis using public high-throughput database revealed a significant downregulation of CRAT in tumor tissues of ovarian cancer (OC), as compared to corresponding normal tissues, implying that CRAT may play a role in the progression of OC." (PMID 39828731, 2025).
asthma (1 paper, 2024). "With respect to increased risk of asthma, blood genes again had the largest relative effect sizes in males (BAG6, CCNG, CRAT, PTPA, and FAM89B), with female training genes exhibiting the largest effects in ATP6V1G2 in the vastus lateralis, ENDOU in white adipose, and CCNF in blood." (PMID 38693125, 2024).
bladder cancer (1 paper, 2022). "CRAT gene was less reported in cancer research and immune microenvironment, but it was identified as prognostic genes in bladder cancer." (PMID 35875026, 2022).
brain aneurysm (1 paper, 2015). A congenital or acquired aneurysm within the cranium. "Our cohort was comprised of healthy Nunavik Inuit individuals and individuals with a family history of brain aneurysms; none of them showed any of the severe symptoms caused by CPTs or CrAT deficiencies." (PMID 26010953, 2015).
cervical cancer (1 paper, 2023). A primary or metastatic malignant neoplasm involving the cervix. "In total, 28 genes (e.g., ATF2, BRCA2, CSRP2BP and EP300) were up-regulated and 16 genes (e.g., CDY1, CHAT and CRAT) were down-regulated in cervical cancer." (PMID 37845756, 2023).
colitis (1 paper, 2024). Inflammation of the colon. "We also observed a decreasing trend in proteins regulating the downstream ketogenesis pathway in colitis, including 3-hydroxy-3-methylglutaryl-CoA lyase (HMGCL), 3-hydroxybutyrate dehydrogenase 1 (BDH1), and carnitine acetyltransferase (CRAT)." (PMID 38668322, 2024).
dermatitis (1 paper, 2024). An inflammatory process affecting the skin. "For example, CRAT is a mitochondrial enzyme that transfers acetyl groups between CoA and carnitine during lipid metabolism and links with dermatitis have not been previously reported." (PMID 38773393, 2024).
dilated cardiomyopathy (1 paper, 2025). Cardiomyopathy which is characterized by dilation and contractile dysfunction of the left and right ventricles. "During myocardial inflammation and dilated cardiomyopathy due to depletion of carnitine acetyltransferase (CRAT), type I IFN responses increase AIM2 expression and AIM2 inflammasome activation in cardiomyocytes." (PMID 39158380, 2025).
Insulin resistance (1 paper, 2017). Increased resistance towards insulin, that is, diminished effectiveness of insulin in reducing blood glucose levels. "Third, insulin resistance and lipid stress inhibit PDH and CrAT in muscle mitochondria thereby increasing susceptibility to mitochondrial dysfunction." (PMID 28150739, 2017).
osteoarthritis (1 paper, 2017). A noninflammatory degenerative joint disease occurring chiefly in older persons, characterized by degeneration of the articular cartilage, hypertrophy of bone at the margins and changes in the synovial membrane. "CRAT expression was suppressed in osteoarthritis chondrocytes, and its knockdown yielded pathological osteoarthritic characteristics, including VLCFA accumulation, apoptosis, autophagic inhibition, and mitochondrial dysfunction." (PMID 29050208, 2017). "CRAT is one of the genes whose was reduced in most osteoarthritis chondrocytes." (PMID 29050208, 2017).
skin aging (1 paper, 2025). The gradual irreversible changes in structure of skin that occur as a result of the passage of time.. "Overexpression of CRAT mitigated this effect, suggesting that epigenetic modulation of CRAT could serve as a potential therapeutic target for preventing UV-induced skin aging." (PMID 40606604, 2025).
viral infections (1 paper, 2024). "Among the top 10 downregulated genes, SREBF1, FGFR4, CRAT and PXMP4 showed a similar decrease following different viral infections." (PMID 39625479, 2024).
cancer (8 papers, 2017 to 2025). A tumor composed of atypical neoplastic, often pleomorphic cells that invade other tissues. "Higher carnitine O-acetyltransferase (CRAT) expression is also known to contribute to maintaining a high metabolic plasticity in cancers and suppressing the carnitine system." (PMID 32131398, 2020). "Conversely, inhibiting CRAT activity may have applications in cancer therapy, where altered lipid metabolism supports tumor growth and proliferation." (PMID 40001519, 2025). "However, the functions of CRAT have rarely been investigated in human cancers, especially in OC." (PMID 39828731, 2025). "In this context, targeting enzymes like CROT, CRAT, CPT2, CPT1, and CAC, which regulate lipid transport and utilization, may inhibit cancer cell growth by disrupting their metabolic flexibility." (PMID 40001519, 2025). "Betaine–homocysteine S-methyltransferase 1 (BHMT), isovaleryl-CoA dehydrogenase (IVD), short-chain specific acyl-CoA dehydrogenase (CRAT) and arginase-1 were all down-regulated in cancer tissues of HCC without PVT and further deceased in the cancer tissues of HCC with PVT." (PMID 28785178, 2017).
tumor (7 papers, 1986 to 2025). "Remarkable upregulation of CRAT in xenograft tumors were validated by IHC analysis, implying that the tumor growth inhibitory role was exerted by forced expression of CRAT." (PMID 39828731, 2025). "Consistently, qRT-PCR analysis in OC tissues and corresponding adjacent non-tumor tissues (n = 30) revealed that the expression of CRAT was also decreased in OC at mRNA level." (PMID 39828731, 2025). "We found that CRAT functions as a critical tumor suppressor during OC progression by enhancing PGC-1α-mediated mitochondrial biogenesis and metabolism." (PMID 39828731, 2025). "In summary, CRAT functions as a critical tumor suppressor in OC progression by enhancing PGC-1α-mediated mitochondrial biogenesis and metabolism, suggesting CRAT as a potential therapeutic target in treatment of OC." (PMID 39828731, 2025). "Here, we used immunohistochemistry to examine the expression of the remaining three components of CS (CACT, CPT2, and CrAT) in a series of 32 spontaneous CMTs and compared their expression with the degree of tumor malignancy." (PMID 34679988, 2021). "Forced expression of CRAT significantly slowed the growth rate of HEY cells in nude mice, as determined by tumor size and weight." (PMID 39828731, 2025). "Together, our study provides a molecular basis for CRAT as a critical tumor suppressor in OC progression by enhancing PGC-1α-mediated mitochondrial biogenesis and metabolism, highlighting CRAT as a promising prognostic marker and therapeutic target in the treatment of OC." (PMID 39828731, 2025).
infection (2 papers, 2021 to 2025). The state of being infected such as from the introduction of a foreign agent such as serum, vaccine, antigenic substance or organism. "The gene FGSG_00840 annotated as carnitine O-acetyltransferase was obviously down-regulated during the infection process with the log2FC value ranging from −2.58 to −3.30." (PMID 34072279, 2021).
kidney disease (1 paper, 2023). "From the datamining sources through network biology conducted by Cytoscape, it was found that ACADM, CROT, CRAT, and ACADS are the most prominent genes involved in the function of LC and in the pathology of kidney disease." (PMID 36836532, 2023).
metabolic disorder (1 paper, 2021). "First of all, muscle-specific CrAT null mice displayed most features of the metabolic disorder as they quickly gained weight, were glucose intolerant, and were insulin resistant." (PMID 33921022, 2021).
mitochondrial disease (1 paper, 2025). "Recent structural studies have focused on understanding CRAT enzyme mechanisms, particularly through the examination of genetic variants like p.Tyr110Cys, which have been linked to mitochondrial diseases, such as Leigh syndrome." (PMID 40001519, 2025).
CRAT also shares sentences with these, for which no sentence is quoted: heart failure (2 papers); alcoholic hepatitis (1); carnitine deficiency (1); Leigh syndrome (1); liver steatosis (1); lung carcinoma (1); prostate carcinoma (1); prostate tumor (1).